GEMIN6 (gem nuclear organelle associated protein 6)
Description:
The SMN complex catalyzes the assembly of small nuclear ribonucleoproteins (snRNPs), the building blocks of the spliceosome, and thereby plays an important role in the splicing of cellular pre-mRNAs. Most spliceosomal snRNPs contain a common set of Sm proteins SNRPB, SNRPD1, SNRPD2, SNRPD3, SNRPE, SNRPF and SNRPG that assemble in a heptameric protein ring on the Sm site of the small nuclear RNA to form the core snRNP (Sm core). In the cytosol, the Sm proteins SNRPD1, SNRPD2, SNRPE, SNRPF and SNRPG are trapped in an inactive 6S pICln-Sm complex by the chaperone CLNS1A that controls the assembly of the core snRNP. To assemble core snRNPs, the SMN complex accepts the trapped 5Sm proteins from CLNS1A forming an intermediate. Binding of snRNA inside 5Sm triggers eviction of the SMN complex, thereby allowing binding of SNRPD3 and SNRPB to complete assembly of the core snRNP.
Synonyms: FLJ23459
Tractability: PROTAC: ubiquitination databases record sites on it.
Gene: Protein-coding gene on chromosome 2 (38,751,534 to 38,785,002, forward strand). Ensembl gene ENSG00000152147.
Subcellular location: Nucleus, nucleoplasm; Nucleus, gem; Cytoplasm
Subcellular location (Human Protein Atlas): Nuclear bodies; Nucleoplasm
Pathways (Reactome):
Disease: SARS-CoV-2 modulates host translation machinery
Metabolism of RNA: snRNP Assembly
Gene Ontology:
Molecular function: protein binding; RNA binding
Biological process: spliceosomal snRNP assembly; mRNA splicing, via spliceosome; spliceosomal complex assembly
Cellular component: cytoplasm; cytosol; Gemini of Cajal bodies; nuclear body; nucleoplasm; SMN complex; SMN-Sm protein complex; nucleus
Genetic constraint (gnomAD): Loss-of-function variants: 13 observed, 15.23 expected, observed/expected ratio (o/e) 0.85, 90% interval 0.56 to 1.36. The upper end of that interval is the gene's LOEUF score, 1.36, which puts it in group 5 of 6, group 1 being the genes least tolerant of losing a copy. Missense variants: 271 observed, 212.97 expected, observed/expected ratio (o/e) 1.27, 90% interval 1.15 to 1.41. Synonymous variants: 87 observed, 73.27 expected, observed/expected ratio (o/e) 1.19, 90% interval 1 to 1.42.
Homologues: Orthologues: chimpanzee GEMIN6 (100% identical), macaque GEMIN6 (98% identical), rabbit GEMIN6 (92% identical), dog GEMIN6 (92% identical), mouse Gemin6 (86% identical), rat Gemin6 (84% identical), guinea pig GEMIN6 (81% identical), pig GEMIN6 (71% identical), tropical clawed frog gemin6 (59% identical), zebrafish gemin6 (27% identical), Caenorhabditis elegans D1007.4 (19% identical).
Diseases named in the same sentence as GEMIN6 in open-access papers:
GEMIN6 is named in the same sentence as 8 diseases in open-access papers, as found by Europe PMC text mining. Sharing a sentence is not in itself a finding about the gene and the disease. The quoted sentences say what the papers report.
nonsmall cell lung cancer (1 paper, 2022). "In nonsmall cell lung cancer, GEMIN6 was found to accelerate AURKB maturation and c-Myc stabilisation to promote the cancer progression, while the clear role of GEMIN6 in LUAD remains to be addressed." (PMID 36284636, 2022).
spinal muscular atrophy (1 paper, 2021). A motor neuron disease that affect the muscles, and characterized by muscle weakness and atrophy resulting from progressive degeneration and irreversible loss of the anterior horn cells in the spinal cord (i.e., lower motor neurons) and the brain stem nuclei. "TDP-43 also regulates processing of Gemin6, a component of the Gem protein complex dysregulated in spinal muscular atrophy, and of CSNK1D, encoding one of the Ser/Thr Kinase CK-1 isoforms, which can phosphorylate up to 29 sites in TDP-43, some of these in response to stress." (PMID 34380047, 2021).
tumor (3 papers, 2022 to 2023). "GEMIN6 is upregulated in LUSC tumor tissues and high expression of GEMIN6 is correlated with poor clinical outcomes." (PMID 37280525, 2023). "HSPD1 and PSMB4 were observed to show strongly interrelated with neoplasm disease (80%) while GEMIN6 is highly interrelated with nervous system diseases (80%)." (PMID 34918006, 2022). "Compared with the normal tissue, GEMIN6 was expressed remarkably higher in a variety of tumor tissues, including LUAD." (PMID 36284636, 2022). "This study showed that the expression of GEMIN6 was significantly higher in tumor tissues than normal tissues, particularly in LUAD, which implied that GEMIN6 might be involved in lung carcinogenesis." (PMID 36284636, 2022).
cancer (1 paper, 2022). A tumor composed of atypical neoplastic, often pleomorphic cells that invade other tissues. "Considering the worse prognosis of patients with overexpression of GEMIN6, we speculated that the high GEMIN6 expression could promote the progression of cancer via participating in cell cycle and replication in LUAD." (PMID 36284636, 2022).
GEMIN6 also shares sentences with these, for which no sentence is quoted: infection (2 papers); lung adenocarcinoma (1); myeloma (1); nervous system diseases (1).